GSG1 (germ cell associated 1)
Description:
May cause the redistribution of PAPOLB from the cytosol to the endoplasmic reticulum.
Synonyms: MGC3146
Tractability: Antibody: UniProt predicts a signal peptide or a membrane-spanning region; its Gene Ontology location is reachable by antibodies, with medium confidence.
Gene: Protein-coding gene on chromosome 12 (13,083,532 to 13,103,683, reverse strand). Ensembl gene ENSG00000111305.
Subcellular location: Endoplasmic reticulum membrane
Gene Ontology:
Molecular function: protein binding
Cellular component: plasma membrane; endoplasmic reticulum membrane
Genetic constraint (gnomAD): Loss-of-function variants: 28 observed, 28.5 expected, observed/expected ratio (o/e) 0.98, 90% interval 0.73 to 1.35. The upper end of that interval is the gene's LOEUF score, 1.35, which puts it in group 5 of 6, group 1 being the genes least tolerant of losing a copy. Missense variants: 421 observed, 442.64 expected, observed/expected ratio (o/e) 0.95, 90% interval 0.88 to 1.03. Synonymous variants: 162 observed, 177.13 expected, observed/expected ratio (o/e) 0.91, 90% interval 0.8 to 1.04.
Homologues: Orthologues: chimpanzee GSG1 (92% identical), rabbit GSG1 (77% identical), dog GSG1 (74% identical), pig GSG1 (74% identical), guinea pig GSG1 (73% identical), rat Gsg1 (70% identical), mouse Gsg1 (67% identical), tropical clawed frog gsg1 (52% identical). Paralogues in human: GSG1L (37% identical), GSG1L2 (28% identical), TMEM202 (13% identical), LIM2 (10% identical), PMP22 (9% identical), CLDND2 (8% identical), NKG7 (8% identical), EMP2 (7% identical), EMP1 (6% identical), EMP3 (6% identical).
Diseases named in the same sentence as GSG1 in open-access papers:
GSG1 is named in the same sentence as 5 diseases in open-access papers, as found by Europe PMC text mining. Sharing a sentence is not in itself a finding about the gene and the disease. The quoted sentences say what the papers report.
pancreatic cancer (1 paper, 2017). "We observed differential methylation of FOSB, KLF6, ATP4A, and GSG1 genes that are previously reported as markers for pancreatic cancer survival." (PMID 28423671, 2017). "We also observed the differential methylation of four pancreatic cancer marker genes, i.e., FOSB, KLF6, ATP4A, GSG1, related to survival of patients." (PMID 28423671, 2017).
GSG1 also shares sentences with these, for which no sentence is quoted: cancer (1 paper); Infertility (1); metastatic disease (1); oral candidiasis (1).